DTWD1 (DTW motif tRNA-uridine aminocarboxypropyltransferase 1)
Description:
Catalyzes the formation of 3-(3-amino-3-carboxypropyl)uridine (acp3U) at position 20 in the D-loop of several cytoplasmic tRNAs (acp3U(20)).
Synonyms: MDS009; MGC111207
Tractability: PROTAC: ubiquitination databases record sites on it.
Gene: Protein-coding gene on chromosome 15 (49,621,031 to 49,656,232, forward strand). Ensembl gene ENSG00000104047.
Subcellular location: Nucleus
Subcellular location (Human Protein Atlas): Nucleoli rim; Mitotic chromosome; Nucleoplasm; Vesicles
Gene Ontology:
Molecular function: tRNA-uridine aminocarboxypropyltransferase activity
Biological process: tRNA modification
Cellular component: nucleus
Genetic constraint (gnomAD): Loss-of-function variants: 27 observed, 29.03 expected, observed/expected ratio (o/e) 0.93, 90% interval 0.68 to 1.28. The upper end of that interval is the gene's LOEUF score, 1.28, which puts it in group 5 of 6, group 1 being the genes least tolerant of losing a copy. Missense variants: 342 observed, 342.39 expected, observed/expected ratio (o/e) 1, 90% interval 0.91 to 1.09. Synonymous variants: 99 observed, 107.85 expected, observed/expected ratio (o/e) 0.92, 90% interval 0.78 to 1.09.
Homologues: Orthologues: chimpanzee DTWD1 (100% identical), macaque DTWD1 (98% identical), dog DTWD1 (91% identical), rabbit DTWD1 (91% identical), guinea pig DTWD1 (88% identical), pig DTWD1 (88% identical), rat Dtwd1 (75% identical), mouse Dtwd1 (74% identical), tropical clawed frog dtwd1 (57% identical), zebrafish dtwd1 (42% identical), Drosophila melanogaster CG2006 (34% identical), Caenorhabditis elegans Y53C12A.10 (27% identical). Paralogues in human: YIPF3 (13% identical).
Diseases named in the same sentence as DTWD1 in open-access papers:
DTWD1 is named in the same sentence as 7 diseases in open-access papers, as found by Europe PMC text mining. Sharing a sentence is not in itself a finding about the gene and the disease. The quoted sentences say what the papers report.
gastric cancer (4 papers, 2016 to 2023). A primary or metastatic malignant neoplasm involving the stomach. "There have been reported that histone deacetylase 2 was increased in human gastric cancer, and histone deacetylase 3 can inhibit the expression of DTWD1, which is a cancer suppressor gene in gastric cancer." (PMID 35463631, 2022). "In the case of Cancer epigenetics, DTWD1 was down-regulated in gastric cancer cell lines and primary gastric carcinoma tissues." (PMID 35057823, 2022). "DTWD1 functions as a tumour suppressor play an important role in the pathogenesis of many cancers, including gastric cancer." (PMID 35057823, 2022).
breast carcinoma (1 paper, 2022). "The expression pattern of DE mRNA according to the tumor stage in mRNAs was downregulated in breast cancer tissue, SYF2 and DTWD1 showed a more down-expressed pattern as the cancer progressed." (PMID 36294892, 2022).
colorectal cancer (1 paper, 2023). A primary or metastatic malignant neoplasm that affects the colon or rectum. "For example, DTWD1 has been discovered as a tumor suppressor, whose inactivating mutations had been identified in colorectal cancer." (PMID 37745798, 2023).
mantle cell lymphoma (1 paper, 2021). Mantle cell lymphoma is a rare form of malignant non-Hodgkin lymphoma affecting B lymphocytes in the lymph nodes in a region called the ``mantle zone''. "It was also found that B cell (DTWD1) could contributed to mantle cell lymphoma." (PMID 34485161, 2021).
tumor (8 papers, 2019 to 2023). "The results showed that the expression of ACACB, ATP8B4, C14orf28, CIRBP, and DTWD1 were higher in normal tissues, and the content of CDC6, DSP, HMGB3, HNRNPA3P1, PPP1R14C, and TPX2 were higher in tumor tissues." (PMID 35778922, 2022).
cancer (6 papers, 2019 to 2023). A tumor composed of atypical neoplastic, often pleomorphic cells that invade other tissues. "Dysregulated expression of DTWD1 has been reported in several malignancies, nevertheless, the role of DTWD2 in cancers remains completely unknown." (PMID 37745798, 2023).
DTWD1 also shares sentences with these, for which no sentence is quoted: melanoma (1 paper).